ARID3B (AT-rich interaction domain 3B)
Description:
Transcription factor which may be involved in neuroblastoma growth and malignant transformation. Favors nuclear targeting of ARID3A.
Synonyms: BDP; DRIL2
Tractability: PROTAC: ubiquitination databases record sites on it; its protein half-life has been measured.
Gene: Protein-coding gene on chromosome 15 (74,541,188 to 74,598,131, forward strand). Ensembl gene ENSG00000179361.
Subcellular location: Nucleus
Subcellular location (Human Protein Atlas): Nucleoplasm
Gene Ontology:
Molecular function: protein binding; DNA binding
Biological process: regulation of transcription by RNA polymerase II
Cellular component: nucleoplasm; nucleus
Genetic constraint (gnomAD): Loss-of-function variants: 10 observed, 51.07 expected, observed/expected ratio (o/e) 0.2, 90% interval 0.12 to 0.33. The synonymous counts are far from expectation, so gnomAD's model fits this gene poorly and the ratio says little. Missense variants: 483 observed, 710.37 expected, observed/expected ratio (o/e) 0.68, 90% interval 0.63 to 0.73. Synonymous variants: 205 observed, 277.29 expected, observed/expected ratio (o/e) 0.74, 90% interval 0.66 to 0.83.
Homologues: Orthologues: chimpanzee ARID3B (99% identical), macaque ARID3B (99% identical), pig ARID3B (89% identical), dog ARID3B (89% identical), rat Arid3b (87% identical), mouse Arid3b (87% identical), guinea pig ARID3B (84% identical), rabbit ARID3B (55% identical), tropical clawed frog arid3b (49% identical), zebrafish arid3b (45% identical), Drosophila melanogaster retn (30% identical), Caenorhabditis elegans cfi-1 (28% identical). Paralogues in human: ARID3A (42% identical), ARID3C (34% identical).
Diseases named in the same sentence as ARID3B in open-access papers:
ARID3B is named in the same sentence as 34 diseases in open-access papers, as found by Europe PMC text mining. Sharing a sentence is not in itself a finding about the gene and the disease. The quoted sentences say what the papers report.
ovarian carcinoma (11 papers, 2011 to 2026). A malignant neoplasm originating from the surface ovarian epithelium. "Since ARID3B regulates the expression of Wnt signaling pathway genes and elevated Wnt signaling is associated with ovarian cancer progression, we examined this relationship." (PMID 26121572, 2015). "Since Wnt signaling is implicated in many type of tumors including ovarian cancer we further investigated regulation of FZD5 by ARID3B." (PMID 26121572, 2015). "With these tools, we showed that phosphorylation confines ARID3B to the nucleus in ovarian cancer and glioblastoma cells, as well as in human tissues, while unphosphorylated ARID3B can localize to the nucleus, cytoplasm, and membrane." (PMID 41972703, 2026). "ARID3B, known for its role in chromatin remodeling and gene expression regulation, promotes cancer stemness and tumor growth in ovarian cancer xenografts." (PMID 39999848, 2025). "ARID3B, as a target of miR-125a, accelerates the migration of breast cancer and invasion of ovarian cancer, which inclines to play as an oncogene." (PMID 33592583, 2021). "In human cancers, ARID3B is considered an oncoprotein, and overexpression of ARID3B has been noted in ovarian cancer 33, neuroblastoma 34, and breast cancer." (PMID 32483441, 2020). "ARID3B has been further described as an oncoprotein and is involved in the progression of malignant neuroblastoma, ovarian cancer, and breast cancer." (PMID 33142733, 2020). "ChIP samples were prepared from Skov3IP and OVCA429 ovarian cancer cells, using both parental lines and cell lines expressing 6XHis-ARID3B." (PMID 26121572, 2015). "The DNA-binding protein AT-Rich Interactive Domain 3B (ARID3B) is elevated in ovarian cancer and increases tumor growth in a xenograft model of ovarian cancer." (PMID 26121572, 2015). "Our first step was to identify regulatory regions (such as promoters and enhancers) bound by ARID3B via ChIP-Chip analysis in ovarian cancer cells overexpressing ARID3B (6XHis-ARID3B)." (PMID 26121572, 2015). "ARID3B promotes tumor growth in neuroblastoma and ovarian cancer, but ARID3B expression decreases with progression of esophageal and stomach cancer." (PMID 26121572, 2015). "We demonstrate that ARID3B binds regulatory regions of target genes in a sequence specific fashion and alters the expression of endogenous target genes in ovarian cancer cell lines." (PMID 26121572, 2015). "In this study we identified direct gene targets of ARID3B in ovarian cancer cells through Chromatin Immunoprecipitation (ChIP) followed by microarray (ChIP-Chip) technology." (PMID 26121572, 2015). "Overexpression of FZD5 or ARID3B in ovarian cancer cells increases adhesion to several ECM proteins, including fibronectin and vitronectin, while knockdown of FZD5 or editing of ARID3B causes a loss of adhesion to certain ECM components." (PMID 26121572, 2015). "To begin to shed light on the molecular mechanisms by which ARID3B regulates ovarian cancer progression, we identified direct targets of ARID3B." (PMID 26121572, 2015). "Our data demonstrates for the first time that ARID3B increases ovarian cancer tumor growth in a xenograft model of ovarian cancer." (PMID 25327563, 2014). "The SKOV3IP-ARID3B xenograft tumors mimic the overexpression of ARID3B found in human ovarian cancer." (PMID 25327563, 2014). "We wanted to establish a xenograft model of ovarian cancer in mice where ARID3B is expressed at comparable levels to what is observed in human tumors." (PMID 25327563, 2014). "Recently we demonstrated that ARID3B is significantly overexpressed in ovarian cancer compared to normal ovarian surface epithelium and benign ovarian tumors." (PMID 25327563, 2014). "To do this we analyzed the expression levels of ARID3B in human ovarian cancer by performing immunohistochemistry (IHC) for ARID3B on ovarian cancer tissue microarrays (TMAs)." (PMID 25327563, 2014).
ovarian carcinoma (continued). "We generated a xenograft mouse model of ovarian cancer that recapitulates the level of ARID3B overexpression found in human tumor sections." (PMID 25327563, 2014). "We previously identified ARID3B as a target of miR-125a, a microRNA that is under expressed in ovarian cancer." (PMID 22860069, 2012). "Due to overexpression of ARID3B in ovarian cancer, we wanted to define the function and regulation of ARID3B in ovarian cancer cells." (PMID 22860069, 2012). "Upon further investigation we discovered that ARID3B is alternatively spliced in ovarian cancer cells." (PMID 22860069, 2012). "To investigate the cellular localization of ARID3B Fl and ARID3B Sh in ovarian cancer cells, we fractionated cells using the Pierce Subcellular Fractionation Kit." (PMID 22860069, 2012). "After examining the expression and localization of ARID3B isoforms, we wanted to determine the functions of these gene products in epithelial ovarian cancer cells." (PMID 22860069, 2012). "Upon determining that ARID3B isoforms were both expressed highly in ovarian cancer cells we wanted to assess if they were regulated by EGFR." (PMID 22860069, 2012). "To determine if ARID3B Sh is expressed in ovarian carcinoma cells we performed reverse transcribed polymerase chain reaction (RT-PCR)." (PMID 22860069, 2012). "miR-125a could target the AT-rich interactive domain 3B (ARID3B) to repress the conversion of highly invasive ovarian cancer cells from a mesenchymal to an epithelial morphology." (PMID 29084594, 2017). "The goal of this study was to mechanistically identify direct target genes of ARID3B that may contribute to ovarian cancer progression." (PMID 26121572, 2015). "FZD5 is highly expressed in ovarian cancer cell lines, and is upregulated by exogenous ARID3B." (PMID 26121572, 2015). "We next demonstrated that ARID3B induces expression of its targets in ovarian cancer cell lines." (PMID 26121572, 2015). "Furthermore, overexpression of ARID3B in ovarian cancer cells accelerates tumor growth in a xenograft model of ovarian cancer." (PMID 26121572, 2015). "Furthermore, our data indicate that ARID3B regulation of direct target genes in the Wnt pathway promotes adhesion of ovarian cancer cells." (PMID 26121572, 2015). "Furthermore, ARID3B overexpression increases the pool of CD133+ spheroids in ovarian cancer cell lines." (PMID 25327563, 2014). "In addition to being overexpressed in ovarian cancer and late stage neuroblastoma, ARID3B is highly expressed in embryonic (ES) and induced pluripotent stem cells." (PMID 25327563, 2014). "Understanding the function of the ARID3B splice forms may lead to a better understanding of the progression of ovarian cancer." (PMID 22860069, 2012). "Expression of ARID3B Sh varied by cell type, but was highly expressed in most ovarian cancer lines." (PMID 22860069, 2012). "The presence of this alternate splice form suggests that multiple splice forms of ARID3B may play a role in the progression of ovarian cancer." (PMID 22860069, 2012). "Our results suggest that regulating the splicing of ARID3B may be important in ovarian cancer progression." (PMID 22860069, 2012). "Since both EGFR and ARID3B are overexpressed in ovarian cancer we wanted to assess if there was a causal relationship between these molecules and ascertain if ARID3B is EGFR-regulated in ovarian cancer cells." (PMID 22860069, 2012). "In addition, miR-125b targets proto-oncogenic BCL3, which can suppress ovarian cancer cell growth, and overexpressed ARID3B in ovarian cancer is a target of miR-125a." (PMID 21541038, 2011). "Specifically, as ARID3B is involved in the mesenchymal phenotype development, ARID3B increase by repression of miR-125a is suggested to promote a mesenchymal morphology and contribute to ovarian cancer progression." (PMID 21541038, 2011). "Therefore we hypothesized that ARID3B may contribute to ovarian cancer growth by impacting cancer stem cell development." (PMID 25327563, 2014).
ovarian carcinoma (continued). "Therefore both forms of ARID3B can be found in ovarian cancer cell lines and ovarian tumors." (PMID 22860069, 2012). "Therefore alternative splice forms of ARID3B may play different roles in ovarian cancer progression." (PMID 22860069, 2012). "To assess if ARID3B modulates changes in adhesion potentially through Wnt signaling, we tested the effects of ARID3B or FZD5 expression in ovarian cancer cells on adhesion to ECM components." (PMID 26121572, 2015). "It should be noted that in all of our experiments using ovarian cancer cell lines (OVCA429, Skov3IP, Skov3, and OVCAR3) it was necessary to use lentiviral transduction to introduce 6xHis-ARID3B, RFP, or FZD5 into the cells." (PMID 26121572, 2015). "Our data demonstrate that ARID3B boosts production of CD133+ cells and increases ovarian cancer progression in vivo." (PMID 25327563, 2014). "Future studies of ARID3B regulation of tumorigenesis and gene regulation in HGSOC cell lines are ongoing and will enable us to better dissect the contribution of ARID3B to ovarian cancer." (PMID 25327563, 2014). "We previously demonstrated that ARID3B, a member of the AT-rich interactive domain (ARID) family of DNA binding proteins, is overexpressed in ovarian cancer." (PMID 22860069, 2012). "RNA was collected from each cell line, cDNA was generated and quantitative RT-PCR (QRT-PCR) was performed for ARID3B Fl, ARID3B Sh and 18 S rRNA (control) (data was normalized to DOV13 ovarian cancer cells)." (PMID 22860069, 2012). "TCF/LEF induced transcriptional activity is induced by ARID3B transfected 293FT cells, but since we were unable to perform TOPFlash assays in our ovarian cancer cells we do not know if ARID3B activation of FZD5 results in TCF/LEF mediated gene expression." (PMID 26121572, 2015). "The target genes that are regulated by ARID3B and the molecular mechanisms by which ARID3B impacts tumorigenesis in ovarian cancer are not known." (PMID 26121572, 2015). "We found that moderate, but not high expression of ARID3B in the nucleus significantly correlates with ovarian cancer relapse." (PMID 25327563, 2014). "To determine whether ARID3BFL overexpression regulates these genes in other ovarian cancer cell lines, we performed qRT-PCR for SFRP1 and WISP1 on OVCA429 cells transduced with RFP or ARID3B." (PMID 25327563, 2014). "Since we found that two of the ovarian cancer (OVCA 433 and OVCA 429) cell lines exhibited high levels of mRNA expression of ARID3B Sh, we wanted to investigate whether ARID3B mRNA levels are regulated in these cell lines by growth factor signaling." (PMID 22860069, 2012). "In this study we demonstrated that ARID3B Fl, but not ARID3B Sh induces apoptosis in ovarian cancer cell lines." (PMID 22860069, 2012). "ARID3B Fl overexpression in ovarian cancer cell lines significantly increased the expression of all nine apoptotic related genes, while ARID3B Sh overexpression failed to do so." (PMID 22860069, 2012). "We provide compelling evidence that in epithelial ovarian cancer cells that ARID3B is not exclusive to the nucleus." (PMID 22860069, 2012). "Our data therefore indicates that ARID3B Fl not ARID3B Sh acts as a pro-apoptotic factor in ovarian cancer cells." (PMID 22860069, 2012). "ARID3B is overexpressed in ovarian cancer and neuroblastoma, but these studies did not distinguish between ARID3B Fl and ARID3B Sh." (PMID 22860069, 2012). "In addition, we made the novel observation, that ARID3B Fl induces apoptosis when overexpressed in ovarian cancer cells while ARID3B Sh does not." (PMID 22860069, 2012). "However, it was not known if ARID3B expression might enhance ovarian cancer tumorgenicity as it does for neuroblastoma." (PMID 25327563, 2014). "The ARID3B Sh splice form was verified using DOV13 and OVCA 429 ovarian cancer cells treated with or without EGF for 24 h." (PMID 22860069, 2012).
ovarian carcinoma (continued). "We transduced human ovarian cancer cells, OVCA 429, with lentiviral particles expressing GFP, ARID3B Fl or ARID3B Sh, and treated cells with or without 20 nM EGF." (PMID 22860069, 2012).
breast carcinoma (7 papers, 2015 to 2022). "ARID3B is one of genes which regulates cell motility and actin cytoskeleton organization and is found to be associated with breast cancer onset." (PMID 26284108, 2015). "In light of these findings, one study showed that overexpression of miR-125b retarded motility and migration behaviors via targeting ARID3B (T-rich interactive domain 3B) in breast cancer cells." (PMID 25605244, 2015). "In addition, it has been shown in a previous study that the complex of Arid3a, Arid3b, and Kdm4c modulates the chromatin configuration of stemness genes for breast cancer by decreasing H3K9me3." (PMID 30616715, 2019). "Low mRNA expression of ARID1A (p=0.0096), ARID2 (p=0.0066), ARID3B (p= 0.000024), ARID5A (p=0.0435), ARID5B (p=0.0022), JARID1A (p=0.0044), JARID2 (p=0.0463) were interrelated with worse OS in grade III breast cancer patients." (PMID 33592583, 2021). "Furthermore, nuclear expression of ARID3B was positively related to ER status and negatively correlated with ERBB2 status, tumor grade and mitotic index in the breast cancer patients." (PMID 33592583, 2021).
neuroblastoma (6 papers, 2012 to 2025). Neuroblastoma (NB) is the most common solid, extracranial childhood tumor. "ARID3B is overexpressed in neuroblastoma and serous OC, and its overexpression is linked to disease recurrence." (PMID 40456746, 2025). "ARID3B is overexpressed in neuroblastoma, particularly stage IV tumors, and cooperates with MYCN to increase oncogenic potential and proliferation." (PMID 26121572, 2015). "ARID3B is expressed in human neuroblastoma cell lines and in stage IV neuroblastoma, but not in stage I-III, indicating a possible role in the progression of malignant neuroblastoma." (PMID 22860069, 2012). "Additionally, ARID3B induces TNF induced death and promotes neuroblastoma and ovarian tumor growth." (PMID 26121572, 2015).
ovarian tumor (4 papers, 2012 to 2019). "To gain insight into how ARID3B regulates ovarian tumor growth we sought to identify ARID3B regulated genes." (PMID 26121572, 2015). "Future experiments will dissect the mechanism for how ARID3B concentration dictates target gene expression and how regulation of these pathways contributes to ovarian tumor growth and metastasis." (PMID 26121572, 2015). "This analysis showed that the level of nuclear ARID3B in SKOV3IP-ARID3BFL tumors was similar to what was observed in 88% of human ovarian tumors." (PMID 25327563, 2014). "This study demonstrates for the first time that ARID3B promotes ovarian tumor development in part by regulating stem cell genes." (PMID 25327563, 2014). "To address this hypothesis, we assessed the role of ARID3B in ovarian tumor growth and determined the effects of ARID3B overexpression on gene expression and drug resistance." (PMID 25327563, 2014). "Recently we reported that the DNA binding protein ARID3B is overexpressed in human ovarian tumors." (PMID 25327563, 2014). "We predict that the subcellular localization of ARID3B may contribute to this discrepancy since ovarian tumors have high levels of cytoplasmic ARID3B Fl." (PMID 22860069, 2012).
colorectal cancer (3 papers, 2020 to 2026). A primary or metastatic malignant neoplasm that affects the colon or rectum. "An increased expression of ARID3B was associated with a better disease-specific survival of obese colorectal cancer patients." (PMID 33142733, 2020). "Furthermore, we had access to an independent dataset from the UK Biobank, in which we validated the association between ARID3B expression and disease-specific survival of obese colorectal cancer patients." (PMID 33142733, 2020). "Another study revealed that KDM4C, recruited by ARID3B (AT-rich interaction domain 3B), drives PD-L1 expression in colorectal cancer stem cells, facilitating immune evasion." (PMID 39519018, 2024). "Finally, we identified ARID3B as a potential survival-modifier in obese colorectal cancer patients." (PMID 33142733, 2020).
serous ovarian cancer (3 papers, 2012 to 2015). "We demonstrated that the DNA-binding protein ARID3B is overexpressed in serous ovarian cancer; ARID3B’s expression in the nucleus correlates with disease relapse." (PMID 26121572, 2015). "We previously demonstrated that ARID3B is overexpressed in human serous ovarian cancer." (PMID 25327563, 2014). "We previously demonstrated that ARID3B is overexpressed in human serous ovarian cancer suggesting that it may play a role in the tumor progression." (PMID 22860069, 2012). "Importantly, ARID3B is overexpressed in serous ovarian cancer." (PMID 22860069, 2012). "Recently we reported that the transcription factor ARID3B, a member of the AT-rich interactive (ARID) family, is overexpressed in serous ovarian cancer." (PMID 25327563, 2014). "Similarly ARID3B overexpressing cells exhibited increased expression of genes (ST3GAL6, ADAM19, and HTATIP2) reported to be part of the serous ovarian cancer ascites CSC signature." (PMID 25327563, 2014).
head and neck cancer (2 papers, 2020 to 2022). A primary or metastatic malignant neoplasm affecting the head and neck. "In our recent study, we linked ARID3B to histone methylation dynamics and elucidated the mechanisms underlying ARID3B-regulated stemness factors in head and neck cancer cells." (PMID 32483441, 2020). "We previously showed that ARID3B regulates the expression of pluripotency genes to enhance the stemness of head and neck cancer." (PMID 32483441, 2020). "We previously demonstrated that in head and neck cancer cells, ARID3B forms a complex with ARID3A." (PMID 32483441, 2020). "The complex composed of ARID3B and ARID3A is directly repressed by Let-7 in head and neck cancer, modulates H3K9me3 at stemness genes, and further regulates cancer stemness." (PMID 36008383, 2022).
colon cancer (1 paper, 2020). "Next, we validated the association between the expression of ARID3B and HES1 expression in 130 samples from colon cancer patients." (PMID 32483441, 2020).
colorectal tumor (1 paper, 2020). "A recent study has described the role of ARID3B in colorectal tumor growth." (PMID 33142733, 2020).